AR (androgen receptor)
Diseases named in the same sentence as AR in open-access papers (continued):
Sharing a sentence is not in itself a finding about the gene and the disease.
tumor (continued). "Given that NKX3.1 is considered to be a tumor suppressor, this suggests a tumor-suppressive function of AR transcriptional activity in 1508 and Leo but not in 1258." (PMID 39201315, 2024). "Nevertheless, and despite the apparently disadvantageous effects of these compounds on AR, when ER is not overexpressed or activated in tumors, AR displays pro-survival and tumorigenic roles, contributing to tumor development." (PMID 39338407, 2024). "In agreement, both PC‐9/AR/shRNA and HCC827/AR/shRNA tumors were significantly responsive to osimertinib, whereas their corresponding control tumors minimally responded to osimertinib as evaluated by measuring both tumor sizes and weights." (PMID 39044361, 2024). "Immunohistochemistry result for breast mass testified strongly positive staining for estrogen receptor (ER) and progesterone receptor (PR) in most tumor cells (3+), 2 + staining for human epithelial receptor 2 (HER-2), 3 + staining for androgen receptor (AR) and 10% positive Ki67 in tumor cells." (PMID 38388422, 2024). "AR expression, PDL-1 and tumor microenvironment can be useful for selecting patients who could be candidates to AR-inhibitors, immunotherapy or other drugs that can effectively act against the cancer." (PMID 39110196, 2024). "Research has indicated that throughout the course of treatment, a significant percentage of CRPC tumours will no longer depend on AR signalling and will take on a wholly distinct histological appearance." (PMID 39682746, 2024). "SR48692 has also demonstrated radiosensitizing effects in PC3 xenografts, reducing tumor burden and enhancing radiation effects in vivo, independent of androgen receptor status." (PMID 39519199, 2024). "For locally malignant hepatoid epitheliomas and carcinomas with low expression of AR and ER receptors, antihormonal therapy makes it possible to reduce the size of the tumor, but does not make it possible to cure it completely." (PMID 36766353, 2023). "In race-specific comparisons, we did not see any significant (p = 0.0996) difference in AR expression between White and Black PCa patients although a decreasing trend was observed in the tumor samples of Black patients." (PMID 38089573, 2023). "(D) Western blot analysis of AR, ARV7, and PSA protein levels in lysed tumor tissues." (PMID 36656639, 2023). "ADH-1 has been tested in preclinical AR negative PCa models but further testing in AR-V7-expressing tumours is worth exploring." (PMID 36937454, 2023). "In addition, western blot analysis indicated that AR, ARV7, and PSA protein levels in the tumor tissues were significantly declined in both 10 and 20 mg/kg Z15 treatment groups." (PMID 36656639, 2023). "Furthermore, immunohistochemistry analysis on tumor samples revealed that SBI-46 severely compromised tumor viability, evidenced by lower expression of the proliferation markers Ki67, AR, AR-v7, and PSA in SBI-46-treated compared to the vehicle-treated mice." (PMID 36980655, 2023). "KIFC1 levels were significantly higher in AR-low and basal-like TNBCs than in AR-high and non-basal-like TNBCs, irrespective of the stage, grade, tumor size, and lymph node status." (PMID 38003261, 2023). "Some of them are under investigation such as circulating tumor cells (CTCs), PTEN, androgen receptor variants, long non-coding RNAs such as HOX transcript antisense intergenic RNA, SChLAP1 and MaLAT-1, and several miRNAs such as miRNA-141 and miRNA-301a." (PMID 37740236, 2023). "However, similar to the results for tumour volume, FEN1 overexpression reversed the decreased expression of Ki67caused by AR knockdown." (PMID 37326412, 2023). "In this study, we sought to determine whether using clinically available drugs targeting both histone deacetylase (HDAC) and PI3K/AKT activities can exploit these vulnerabilities in treatment-resistant AR-positive CRPC and AR-negative NEPC tumor phenotypes." (PMID 37823778, 2023).
tumor (continued). "Some of these studies discovered that the extracts of cannabis enhanced with CBD effectively reduced the growth of tumors in androgen receptor- positive LNCaP xenografts but amplified tumor growth in androgen receptor-negative DU-145 xenografts." (PMID 36853473, 2023). "Clinical: CA 15.3, ACE, and CA-125 values.Pathological: ER, PR, HER2 expression, Ki-67 index, AR (AR: Androgen Receptor), EGFR, SBR grade, and cytokeratin (CK) 5/6 tumor expression.Radiomics: SUVmax at baseline and after the first cycle, in addition to the relative difference between them (ΔSUVmax)." (PMID 37958461, 2023). "The luminal androgen receptor subtype, for example, was characterized by the highest proportion of epithelial cells positive for androgen receptor (AR+LAR), and the mesenchymal tumour subtype contained the greatest proportion of all three stromal cell phenotypes." (PMID 37674077, 2023). "Previous studies have found that expression of METTL3 and WTAP are regulated by androgen in PC cell lines, as well as increased expression of METTL3 plays a pro-tumor role in PC, while METTL3 silencing resulted in upregulation of AR, together with 134 AR-regulated genes." (PMID 38042806, 2023). "However, the role of AR gene rearrangements is incompletely understood, which can be attributed to their heterogeneity in CRPC tissues and circulating tumor DNA (ctDNA)." (PMID 37636316, 2023). "AR signalling refers to DHT binding to AR as a ligand induces its activation to be imported into the nucleus, where AR binds to the androgen response element (ARE), which in turn acts as a transcriptional activator to promote biological functions such as tumour cell proliferation and invasion." (PMID 37328487, 2023). "Immunohistochemistry revealed that the tumor cells diffusely and strongly expressed cytokeratin, synaptophysin, chromogranin A, GATA3, CAM5.2, and estrogen and progesterone receptors; partially expressed AR and GCDFP15." (PMID 38115331, 2023). "Thus, in both LNCaP and MDA PCa 322-2-6a models, inhibition of GR by mifepristone inhibited tumor growth in ENZA-resistant tumors, but the effect was transient, suggesting AR- and GR-independent resistance mechanics." (PMID 37930121, 2023). "Expression of the androgen receptor (AR) in the original tumor of YCU-SDC-14 was not retained after passaging in PDXs or orthotopically transplanted organoids." (PMID 36538240, 2023). "Additionally, in the tumor specimens of advanced PCa patients, we observed low TOMM20 but high NCAM1 expression in the AR negatve PCa cells." (PMID 37563661, 2023). "In some patients with CRPC, the tumor lesions exhibit a particularly aggressive form of disease, with low to no AR expression (AR-null), often showing undifferentiated neuroendocrine features." (PMID 37894914, 2023). "Based on the available research, it appears that the majority of the AR-FL regulated genes are also co-regulated by AR-Vs, presumably due to: the co-existence of both forms in a majority of CRPC tumours; their similar structure; and the fact that they can heterodimerise to drive transcription." (PMID 36937454, 2023). "The androgen receptor could also activate JAK/STAT3 and stimulate cell proliferation and antiapoptotic effect increasing tumour invasion." (PMID 38137361, 2023). "Therefore, this study aimed to investigate the role of AR and AR-regulated tumor suppressor NKX3.1 upon oxidative stress-induced DNA damage response (DDR) in the inflammatory tumor microenvironment of the prostate." (PMID 38155939, 2023).
tumor (continued). "Approximately 20% of castration-resistant adenocarcinomas can further progress to an AR-negative neoplasm called “neuroendocrine prostate cancer” (NEPC)." (PMID 36674949, 2023). "Moreover, MiR-181 has been found to facilitate PCa cell proliferation and tumor development in mice through regulation of DAX1, an androgen receptor negative regulator." (PMID 38047026, 2023). "This modulation is also observed in RNA-seq of HCI-009, an AR+ PDX tumor grown in mice with or without DHT, which showed significant upregulation of RUNX1 (fold change = 1.84, p = 1.27 × 10−3)." (PMID 36766786, 2023). "Indirect validation of our approach was provided by the significant associations between high levels of progesterone receptor (PR), estrogen receptor (ER), androgen receptor (AR), GATA3 expression, and favorable tumor features as well as prolonged overall survival." (PMID 38137396, 2023). "In the present study, we examined the effects of these novel HSP70 inhibitors in combination with ARSI treatment and inhibition of AR/AR-V7 signaling using drug-resistant CRPC cell line, conditional reprogrammed cell cultures (CRCs), organoids, and xenograft tumor models." (PMID 36773708, 2023). "Additional HOXB3 had no influence on testosterone generation and AR-target genes expression in tumor cells." (PMID 36973255, 2023). "The activation of the ER induced by estrogen in ER-positive/AR-negative cells or the AR induced by androgen in ER-negative/AR-positive cells promote tumor growth." (PMID 37681860, 2023). "There would be no ligand for the AR, the tumor would not grow, and PSA concentration would decrease." (PMID 38106489, 2023). "For locally malignant tumors of the epithelioma type and carcinomas with low expression of AR and ER receptors, antihormonal therapy makes it possible to reduce the size of the tumor, but does not make it possible to cure it completely." (PMID 36766353, 2023). "We assume that AR-V mRNA expression does not have a major mechanistic role in tumor progression, but rather is a side effect of elevated levels of AR pre-mRNA." (PMID 37016463, 2023). "We found that DBNDD1 expression was positively correlated with the AR in normal prostate tissues but not significant in tumor prostate tissues." (PMID 37569304, 2023). "Together, these results indicated HOXB3 drove CRPC tumor growth and abiraterone resistance independent of A/AR signaling." (PMID 36973255, 2023). "Herein, we measured ERα, ERβ, PGR, and AR protein expression in archived paired malignant and non-malignant colonic tissues, and the results were analyzed based on gender, age, and tumor sidedness." (PMID 37206439, 2023). "In malignant tissues, the proteins of ERα and AR increased significantly and concurred with decreases in ERβ and PGR, and the tumor clinical characteristics correlated positively with ERα and AR, whilst negatively with ERβ and PGR, supporting the contributions of receptors to colon carcinogenesis." (PMID 37206439, 2023). "In particular, the expression of ER and AR showed a negative correlation not only with total immune content in the tumor microenvironment but also with certain immune cell subsets such as macrophages and CD4+ T cells." (PMID 36721218, 2023). "Expression of KDM5B showed positive correlation with AR in non-malignant (R = 0.72, p < 0.01) and tumor specimens (R = 0.44, p < 0.01)." (PMID 37152294, 2023). "Moreover, the protein expression of ERα and AR in malignant tissues showed significant positive correlations, whereas ERβ and PGR correlated negatively, with older age, tumour size, N stage, numbers of positive lymph nodes, and advanced cancer stage." (PMID 37206439, 2023). "Furthermore, the average tumor weights of mice receiving Di-PP/DTX and Di-PP/AR-siRNA were both noticeably lower than those of mice treated with the corresponding naked DTX and siRNA (p < 0.01)." (PMID 35631549, 2022).
tumor (continued). "EGF pathways play a pivotal role in regulating AR signalling, e.g., ERBB1 (EGFR) expression is enhanced as a function of tumour severity, whilst the expression of ERBB2 (HER2) increases during and following androgen ablation, thus ensuring sustained survival of PCa cells." (PMID 35326402, 2022). "The immunohistochemical analysis identified PSA and androgen receptor positive tumor cells in both metastatic lesions, while no variable cancer cells were detected in the prostate on second biopsy." (PMID 35183184, 2022). "The MAT subgroup comprised six tumours with apocrine morphology, hormone receptor negative status, expression of luminal CKs and high rates of AR signalling at transcriptional level." (PMID 34537861, 2022). "Another interesting observation was the upregulation of the androgen receptor (AR gene) in PC-3 cells grown at 18% O2, which is contrasting with fact that PC-3 is derived from an androgen-insensitive tumor and do not express AR." (PMID 36421698, 2022). "We also used specific tumor markers to identify the organoids derived from specific subtypes of SGTs, e.g. MUC4 was used to identify MEC, DOG1 and SOX10 were used to identify AciCC, and HER2 and AR were applied to identify SDC." (PMID 36527158, 2022). "Increased expression was also observed by us in the peritumoral region (control in our model); however, the increase in AR expression in this region is not indicative of an increase in AR in healthy tissues (relative to the tumor core)." (PMID 36361793, 2022). "The elevated intra-tumor level of androgens stimulates AR paracrine and autocrine activation, regardless of serum androgen levels." (PMID 36176747, 2022). "The remaining questions to answer include: STEAP1–4 expression patterns in different grades of PCa, the role of AR in regulating STEAP1–4 expression, other mechanisms by which STEAP1–4 promote PCa pathogenesis, and the roles of STEAP1–4 in the PCa tumor microenvironment." (PMID 36011027, 2022). "Pearson correlation analysis further confirmed the positive correlation between ZFHX3 expression levels and AR activity scores regardless of tumour stage, grade, metastasis or age (data not shown)." (PMID 34953044, 2022). "Androgen receptor (AR), a transcriptional activator of ADAR1 promoter, could suppress circARSP91 expression by upregulating ADAR1 p110, eventually leading to HCC tumor growth both in vitro and in vivo." (PMID 35898396, 2022). "A decreased expression of AR was seen in grade 3 tumours, with the presence of tumour necrosis, and was negative in 84.6% of patients with lymphocytic infiltration." (PMID 35463732, 2022). "Seviteronel, another AR antagonist, did not provide objective tumour responses in locally advanced or metastatic TNBC patients." (PMID 35267409, 2022). "Discovery and development of novel AR degraders could go a long way in offsetting drug resistance as demonstrated using PROTAC that degraded fAR and inhibited tumor cell growth even in models overexpressing AR-V7." (PMID 36078112, 2022). "During this transition, dependence on AR is often lost, and enhanced EGFR-mediated signaling may promote tumor progression." (PMID 35804847, 2022). "Therefore, we uncovered a novel positive feed-forward loop linking AR and ZIC5 in PCa tumor malignant progression." (PMID 36127329, 2022). "BCI (H/I) provides distinct information regarding tumor biology, as evidenced by the lack of correlations with ER, PR, AR and Ki67." (PMID 36527133, 2022). "Since AR ChIP using xenograft tumor tissue has not been reported elsewhere, we first optimized it in the following ways." (PMID 35365763, 2022). "The inhibition of AR signaling via enzalutamide treatment upregulates GRP78 (binding immunoglobulin protein), activates the Wnt/β-catenin pathway, and upregulates miR-29b in tumor cells." (PMID 35447888, 2022). "Of these patients, 58 patients had available tumor specimens for AR testing, with 20 (34.5%) being AR-positive and 38 (65.5%) being AR negative." (PMID 35711833, 2022).
tumor (continued). "It was speculated that in the presence of AR, MMP-2 in EOC cells involved in basal layer degradation and promoted ovarian cell adhesion to the peritoneum and momentum, promoting tumor cell migration." (PMID 35886904, 2022). "It was reported that AR was recognized and bound to AR elements of a Maspin promoter in tumor cells which negatively regulated Maspin expression, but this phenomenon was not confirmed by reexpressing AR in a PC3 cancer cell line." (PMID 36523976, 2022). "Further study found that IMPPE inhibited both full-length and LBD-lacking AR activity at a relatively high dose (>10 μM) and suppressed 22RV1 but not PC-3 cell-derived xenograft tumor growth at a dose of 25 mg/kg/day in castrated nude mice." (PMID 35372068, 2022). "We also analyzed expression of AR (one of the primary targets of CRPC treatments), cleaved PARP (apoptotic marker) and Ki67 (proliferation marker) by immunohistochemistry (IHC) in paraffin‐embedded tumor tissues." (PMID 35612714, 2022). "Taken together, these data uncover a regulatory mechanism by which AR deletion induces IGFBP3 expression in Gli1-lineage FB to block IGF1-signaling activation, further hindering prostatic basal epithelial cell-mediated oncogenesis and tumor development." (PMID 36323713, 2022). "The mechanism of resistance also includes the restoration of AR signaling without AR alterations, including intracrine androgen biosynthesis and AR cofactor alterations in the tumor microenvironment." (PMID 36430730, 2022). "It is particularly interesting that our results show that UGT2B28 is regulated by AR and AR-v7 at the genetic level, and its tumor promoting role is not fully compromised by castrated mouse models or the ablation of AR or androgens." (PMID 35954173, 2022). "The combination of apocrine morphology, hormone receptor negative status and AR expression in a subset of HER-2 positive tumours and TNBCs identifies some but not all MATs." (PMID 34537861, 2022). "AR regulates multiple molecular pathways that are related to tumorigenesis and tumor progression by both transcriptional and non-transcriptional mechanisms." (PMID 35203574, 2022). "Enhanced AR transcription or increased stability of AR protein/mRNA is sufficient to upregulate AR levels without AR gene amplification, and can facilitate tumor growth despite minimal androgen." (PMID 35864113, 2022). "A subtlety of our findings is that tumor AR activity, but not AR abundance, predicted clinical outcomes for patients on BAT." (PMID 36194476, 2022). "Additionally, ARD-69 effectively reduced AR and PSA protein expression in VCaP xenograft tumor tissues." (PMID 35370971, 2022). "Therefore, the progression from low tumor burden mHSPC to high tumor burden mHSPC and then to CRPC reflects the alterations in the AR gene." (PMID 39280893, 2022). "The contribution of AR signaling to HCC progression has been supported with abundant clinical and pre-clinical evidence showing its correlation with faster disease progression, tumor burden, disease prognosis, overall survival, and as a mediator of metastasis." (PMID 36430245, 2022). "The authors describe AR as a favorable marker in RCC that is correlated with a low stage or grade as well as with primary tumor tissues rather than metastases." (PMID 36552000, 2022). "Although the source of tumor heterogeneity in CRPC remains unclear, it is increasingly recognized that this phenomenon contributes to second-generation AR antagonist resistance and NEPC progression." (PMID 35864113, 2022). "However, an androgen-independent tumor differentiates further, triggered by activation of the PI3K/Akt pathway into an AR-phenotype in 11–24% of patients, rendering the AR antagonist treatment ineffective." (PMID 35453603, 2022). "The interaction of specific co-activating proteins with AR, including JMJD2C, LSD1, 37CBP/P300, p160/SRC, and SUV39H2, can drive enhanced AR activation and the concomitant upregulation of the AR-dependent genes to augment tumor growth." (PMID 35954408, 2022).